SUMO2 (small ubiquitin like modifier 2)
Diseases named in the same sentence as SUMO2 in open-access papers (continued):
Sharing a sentence is not in itself a finding about the gene and the disease.
chondrosarcoma (3 papers, 2021 to 2022). A malignant cartilaginous matrix-producing mesenchymal neoplasm arising from the bone and soft tissue. "We demonstrated increased expression of SUMO1 and SUMO2/3 in high-grade chondrosarcomas, associating SUMO expression with tumor progression and increased aggressiveness." (PMID 34359724, 2021). "In chondrosarcoma, it has been shown that the increased expression of SUMO1 and SUMO2/3 is associated with tumor progression and aggressiveness; SUMO2/3 levels are also correlated with poorer survival." (PMID 35465332, 2022). "SUMO1 and SUMO2/3 expression are positively correlated with increased aggressiveness of chondrosarcomas, and patients with high SUMO2/3 expression have poorer survival outcomes." (PMID 36078118, 2022). "We found that SUMO2/3 expression correlates with high histological grade in chondrosarcoma and predicts poor clinical outcome." (PMID 34359724, 2021). "Analyzing different tumor subsets, central chondrosarcoma and peripheral chondrosarcoma, separately showed that high SUMO2/3 expression significantly decreased overall survival in peripheral chondrosarcoma (p = 0.0298)." (PMID 34359724, 2021). "Using immunohistochemistry on tissue microarrays (TMA) containing 137 chondrosarcomas, we showed that higher expression of SUMO1 and SUMO2/3 correlates with increased histological grade." (PMID 34359724, 2021).
glioblastoma (3 papers, 2021 to 2024). The most malignant astrocytic tumor (WHO grade IV). "Since SUMO2 expression is found to be high in glioblastoma tumour-initiating stem cells, SUMO2 targeting is expected to greatly benefit in controlling tumour recurrence." (PMID 34715855, 2021). "Cellularly, both bulk and glioblastoma cancer stem cell-like population and as well as pro-tumourigenic macrophages/stromal cells over-expressed SUMO2 isoform." (PMID 34715855, 2021). "Since inflammation-driven immune escape and fibrosis (ECM stiffening) are key processes that drive glioblastoma pathogenesis, the high expression of SUMO2 in inflammation-promoting macrophages and stromal cells indicates that it may be crucial in their maintenance." (PMID 34715855, 2021). "Protein levels of SUMO1, SUMO2/3 and Ubc9 are upregulated in patient samples derived from astrocytic tumors, with a moderate upregulation in low-grade astrocytoma (grade 2) and anaplastic astrocytoma (grade 3), and a massive upregulation in glioblastoma multiforme (GBM; grade 4)." (PMID 34503213, 2021). "Thus, our study calls for an urgent industry-academia collaborations to develop and validate SUMO2 isoform-specific inhibition strategies, which can target multiple hub pro-tumorigenic genes in glioblastoma pathology, irrespective of patient age and other clinicopathological parameters." (PMID 34715855, 2021).
latent infection (3 papers, 2013 to 2021). "Further investigation revealed that SUMOylation of HNRNPU is greatly enhanced by KSHV latent infection, while only the SUMO2/3- and not the SUMO1-modified form of HNRNPU induced by KSHV responds to hypoxia." (PMID 34726485, 2021). "Taken together, this data above strongly support our hypothesis that KAP1 and Sin3A particularly SUMO-2 modified forms are indeed sensitive to hypoxic stress and are recruited by the LANASIM motif during KSHV latent infection to silence the RTA promoter under normoxic conditions." (PMID 24278015, 2013).
lymphoma (3 papers, 2017 to 2019). A malignant (clonal) proliferation of B- lymphocytes or T- lymphocytes which involves the lymph nodes, bone marrow and/or extranodal sites. "Noteworthy, SUMO-2/3 overexpression was seen in all BLs but was less prevalent in other lymphomas whereas SUMO-1 overexpression was found in all lymphomas." (PMID 31405039, 2019). "C-Myc not only regulates cell biological function but is also involved with sumoylation regulators, such as SUMO2/3 and E1/2/3 ligases, which are in turn regulated by arsenic and contribute to degradation of EBV lytic gene expression in lymphoma cells." (PMID 28637474, 2017).
neuroblastoma (3 papers, 2011 to 2024). Neuroblastoma (NB) is the most common solid, extracranial childhood tumor. "We previously showed that Ubc9 levels were well correlated with SUMO-1 and SUMO-2,3 conjugation levels in hibernating squirrels and the human neuroblastoma cell line SHSY5Y, and those with higher SUMO conjugation levels were more tolerant to ischemic insult." (PMID 22016779, 2011). "We next transfected N2a neuroblastoma cells with myc-Ago2, the SUMO conjugating enzyme Ubc9, and conjugatable or non-conjugatable (lacking the C-terminal diglycine motif required for conjugation) YFP-tagged SUMO1 and SUMO2." (PMID 26188511, 2015).
Alzheimer disease (2 papers, 2009 to 2013). A progressive, neurodegenerative disease characterized by loss of function and death of nerve cells in several areas of the brain leading to loss of cognitive function such as memory and language. "Tau, an Alzheimer's disease associated protein, has been reported to be SUMOylated by SUMO-1, and to a much lesser extent by SUMO-2 or SUMO-3 simultaneously." (PMID 23382880, 2013).
frontotemporal dementia (2 papers, 2024). Frontotemporal dementia (FTD) comprises a group of neurodegenerative disorders, characterized by progressive changes in behavior, executive dysfunction and language impairment, as a result of degeneration of the medial prefrontal and frontoinsular cortices. "We expressed a mutant form of Tau, TauP301L, which is associated with frontotemporal dementia, (FTD) for 17 weeks, and found that TauP301L induces an increase in SUMO2 conjugation." (PMID 39726633, 2024). "To achieve this, we infected JNPL3 mice, an animal model of frontotemporal dementia (FTD) carrying the human P301L mutation in the Tau gene, and aged-matched C57 wild-type animals (WT) with adeno-associated viruses (AAVs) to express NCAP alone or in combination with SUMO2." (PMID 39000276, 2024).
liver cancer (2 papers, 2019 to 2021). An epithelial or non-epithelial malignant neoplasm that arises from the liver. "The expression levels of SUMO1, SUMO2 and SUMO3 in liver cancer cells were significantly higher than those in normal cells (p < 0.01)." (PMID 34830854, 2021). "Further studies have shown that the overexpression of SUMO2/3 reduces the proliferation ability of liver cancer cells but does not affect the migration of liver cancer cells." (PMID 34830854, 2021). "We have shown that Ssd can significantly inhibit the expression of SUMO1 but not SUMO2/3, thereby promoting GLI activation, which is important for the promotion of liver cancer." (PMID 31616295, 2019).
Multiple myeloma (2 papers, 2020 to 2025). "A small molecule inhibitor—TAK-981—that selectively inhibits SUMO2 is currently in phase 1/2 clinical trial for Non-Hodgkin lymphoma (NCT04074330) and phase 1b/2 for refractory multiple myeloma (NCT047760180)." (PMID 40804185, 2025).
myocardial infarction (2 papers, 2021 to 2022). Gross necrosis of the myocardium, as a result of interruption of the blood supply to the area, as in coronary thrombosis. "In the present study, firstly, we validated that the discrepancy in the intracellular localization of SUMO2 and γ-actin and the status of DNA damage in a mouse model of myocardial infarction and H9c2 cell model of hypoxia reoxygenation." (PMID 35864967, 2022). "However, little is known about the protein substrates that are SUMOylated by SUMO2 in myocardial infarction." (PMID 35864967, 2022). "On the other hand, we recently proposed that SUMO2 might exhibit cardioprotective activity via increasing SUMOylation of specific proteins in myocardial infarction." (PMID 35864967, 2022). "Thus, SUMO2-mediated SUMOylation may be a potential therapeutic target for the development of drugs against myocardial infarction." (PMID 34588985, 2021). "Therefore, the present study pursued two specific aims: 1) To explore whether puerarin could protect cardiomyocytes against myocardial infarction via up-regulating SUMO2 and related protein SUMOylation; 2) To discover the molecular mechanisms by which puerarin induced SUMO2 expression." (PMID 34588985, 2021). "Along this line, we previously demonstrated that plant-derived C-glycosylated isoflavone puerarin exhibited effective cardioprotective potential in a mouse model of myocardial infarction via enhancing SUMO2-mediated SUMOylation without affecting SUMO1 expression." (PMID 35864967, 2022).
asthma (1 paper, 2023). "Compared with the control group, the expression of Fos, Myl9 and Tlr4 in the asthma model was increased, while the expression of Smg7, Sumo2 and Stat5a was decreased." (PMID 36726128, 2023). "Additionally, based on the previously published literatures on asthma and inflammation, we screened out down-regulated genes, such as Smg7, Sumo2, and Stat5a, and up-regulated genes, such as Myl9, Fos and Tlr4." (PMID 36726128, 2023). "Therefore, we speculate that Sumo2 may also play a role in asthma, and lncRNA NONMMUT008873 may play regulatory role in inflammation and oxidative stress by positively regulating transcriptional level of Sumo2 mRNA during asthma." (PMID 36726128, 2023).
atherosclerosis (1 paper, 2025). A disease characterized by the build-up of fatty material and calcium deposition in the arterial wall resulting in partial or complete occlusion of the arterial lumen. "Although the redox-sensitive sentrin/Small Ubiquitin-like Modifier (SUMO)-specific protease 3 (SENP3), which preferentially deconjugates SUMO2/3, has been linked to oxidative stress, its role in atherosclerosis remains poorly defined." (PMID 41307849, 2025).
bone osteosarcoma (1 paper, 2018). A usually aggressive malignant bone-forming mesenchymal neoplasm arising from the bone. "Further, SUMO-2,3 protein expression is required for human bone osteosarcoma epithelial cells to survive heat shock in27." (PMID 30065345, 2018).
cerebral infarction (1 paper, 2011). An ischemic condition of the brain, producing a persistent focal neurological deficit in the area of distribution of the cerebral arteries. "Most importantly, there were striking reciprocal relationships between SUMO-1 (and SUMO-2,3) conjugation levels and cerebral infarction volumes among all tested animals, suggesting that the limit in cytoprotection by global SUMOylation remains undefined." (PMID 22016779, 2011).
chronic hepatitis B (1 paper, 2015). "Because all the liver tissues used in present study were collected from the patients with chronic hepatitis B, we assume that SUMO2/3 up-regulation may be caused by inflammatory stimuli." (PMID 26458400, 2015). "SUMO2/3-p65 interaction may be a novel mechanism involved in the transformation from chronic hepatitis B to HCC via stabilizing cytoplasmic p65, which might shed light on understanding the tumorigenesis and development." (PMID 26458400, 2015). "SUMO2/3-p65 interaction may be a novel mechanism involved in the transformation from chronic hepatitis B to HCC via stabilizing p65 in cytoplasm and limiting NF-κB activation, which might shed light on understanding the mechanisms of tumorigenesis and development." (PMID 26458400, 2015).
co-infection (1 paper, 2025). "Importantly, these differences were not due to differences in IAV infection/replication efficiency caused by the pre-infecting paramyxovirus, as determined by co-infection immunostaining, assessment of IAV protein levels, or assessment of changes in global SUMO2/3-conjugated protein levels." (PMID 40920817, 2025).
Cognitive impairment (1 paper, 2024). Abnormal cognition is characterized by deficits in thinking, reasoning, or remembering. "We found that NCAP significantly reduced the performance of the WT animals compared with the WT animals injected with GFP, and we found that that SUMO2 overexpression rescued the cognitive impairment caused by NCAP in the WT mice (two-way ANOVA; AAV effect: p = 0.018, arm effect: p = 0.0006)." (PMID 39000276, 2024). "Together, these data suggest that NCAP can induce cognitive impairment in WT animals and worsen the cognitive impairment already present in JNPL3 mice and that increasing SUMO2 conjugation can improve or restore cognition." (PMID 39000276, 2024).
colon cancer (1 paper, 2016). "This supports previous findings in which RARRES1 expression was associated with SUMO2 expression in HCT116 colon cancer cells." (PMID 27286452, 2016).
colorectal cancer (1 paper, 2025). A primary or metastatic malignant neoplasm that affects the colon or rectum. "All evaluated tumor samples demonstrated robust target engagement following subasumstat administration; SUMO2/3 inhibition was observed in most post-dose samples, except for two patients with MSS colorectal cancer and one patient with NSCLC." (PMID 41134690, 2025).
COVID-19 (1 paper, 2022). A disease caused by infection with severe acute respiratory syndrome coronavirus 2. "Moreover, we highlight the increase in SUMO2 and the enrichment of the SUMOylation of protein pathways as an important process to consider in the dysregulation of the endothelium in COVID-19." (PMID 36142365, 2022).
diabetic nephropathy (1 paper, 2022). "Studies have found that the SUMOylation of SMAD4 induced by SUMO2/3 plays a crucial role in renal fibrosis associated with diabetic nephropathy." (PMID 35707278, 2022).
endothelial dysfunction (1 paper, 2021). In vascular diseases, endothelial dysfunction is a systemic pathological state of the endothelium (the inner lining of blood vessels) and can be broadly defined as an imbalance between vasodilating and vasoconstricting substances produced by (or acting on) the endothelium. "It was reported that endogenous SUMO2 was important in maintaining normal endothelium-dependent vascular function, and SUMO2 upregulation disrupts the balance of the vascular environment and leads to endothelial dysfunction due to cholesterolemia." (PMID 34638970, 2021).
Endotoxemia (1 paper, 2023). "The most significant effect of endotoxemia was the progressive late smear of 150-260KDa SUMO2/3 signal by 24h." (PMID 37520526, 2023). "Endotoxemia induced an early 70KDa SUMO2/3 signal at 1.5h only." (PMID 37520526, 2023). "In the spleen, endotoxemia induced a distinct temporal and substrate specificity for SUMO1 and SUMO2/3, and both were inhibited by TAK981." (PMID 37520526, 2023). "Quantitative comparative analyses show that the most significant effects of endotoxemia were early SUMO1 signals at 100 and 150KDa, and late p250 and early SUMO2/3 signal at 70KDa, and late 260KDa smear." (PMID 37520526, 2023).
esophageal squamous cell carcinoma (1 paper, 2021). Esophageal squamous cell carcinoma (ESCC) is a type of esophageal carcinoma (EC) that can affect any part of the esophagus, but is usually located in the upper or middle third. "In esophageal squamous cell carcinoma, HSP27 can directly interact with SUMO2/3, and SUMOylation of HSP27 enhances tumour cell proliferation, migration and invasion." (PMID 33951297, 2021).
fibrosarcoma (1 paper, 2017). A malignant mesenchymal fibroblastic neoplasm affecting the soft tissue and bone. "Arc was ectopically expressed in HT-1080 fibrosarcoma cells together with His6-tagged SUMO1, SUMO2, or SUMO3." (PMID 28553222, 2017).
follicular thyroid carcinoma (1 paper, 2025). "In thyroid tissue, papillary thyroid carcinoma (PTC) had increased SUMO1 and SENP5 expression, follicular thyroid carcinoma (FTC) showed higher SUMO1 levels, and undifferentiated thyroid carcinoma (UTC) exhibited elevated SUMO1, SUMO2/3, UBC9 and SENP5 levels." (PMID 41268439, 2025).
hepatitis B (1 paper, 2015). "In the early stage of hepatitis B, only a few cells were SUMO2/3-positive, and SUMO2/3 mainly localized in the nuclei." (PMID 26458400, 2015).
herpesvirus infections (1 paper, 2018). "It will be interesting to determine how the interplay between viral proteins that increase and decrease SUMOylation contribute to herpesvirus infections and why UL54 preferentially induces SUMO2 modifications while its homologues in EBV and CMV induce SUMO1 modifications." (PMID 29979787, 2018).
HIV-1 infection (1 paper, 2022). The type species of lentivirus and the etiologic agent of acquired immunodeficiency syndrome (AIDS). "Of note, we have seen in vitro in HEK293 and Jurkat cells that HIV-1 efficiently reduces sumoylation by both SUMO1 and SUMO2/3, implying that both paralogs may actually antagonize HIV-1 infection in vivo, though further studies are needed to explore this." (PMID 35181598, 2022).
Huntington disease (1 paper, 2022). Huntington disease (HD) is a rare neurodegenerative disorder of the central nervous system characterized by unwanted choreatic movements, behavioral and psychiatric disturbances and dementia. "In addition, SUMO2-modified Htt is primarily found in the insoluble fractions from post-mortem tissue from Huntington’s disease cases suggesting that SUMOylation is involved in the pathogenic deposition aggregated proteins." (PMID 35567706, 2022).
hypertrophic cardiomyopathy (1 paper, 2020). A condition in which the myocardium is hypertrophied without an obvious cause. "Interestingly, an inverse correlation of expression levels of SUMO2 and HectD3 was observed in human heart samples from hypertrophic cardiomyopathy patients." (PMID 33037313, 2020).
intrauterine growth restriction (1 paper, 2017). "In support for a key regulatory role of SUMO-2 in placental development, the heterozygous knockout mice for SUMO-2 demonstrate severe intrauterine growth restriction." (PMID 28545138, 2017).
ischemic cardiomyopathy (1 paper, 2016). Ischemic cardiomyopathy is a cardiomyopathy in which a weakness in the muscle of the heart due to inadequate oxygen delivery to the myocardium with coronary artery disease being the most common cause. "A strong increase in SUMO2-mediated sumoylation was also observed in the myocardium of human patients suffering of dilated (DCM) or ischemic cardiomyopathy (ICM), implying an association of SUMO2 with human disease." (PMID 27767176, 2016).
large cell lung carcinoma (1 paper, 2025). "Small cell lung cancer (SCLC) demonstrated higher levels of SUMO1, SUMO2/3, and UBC9, whereas large cell lung carcinoma (LCC) showed markedly reduced SENP1 expression." (PMID 41268439, 2025).
osteosarcoma (1 paper, 2023). A usually aggressive malignant bone-forming mesenchymal neoplasm, predominantly affecting adolescents and young adults. "To facilitate the initial experiments for investigating the sumoylation substrates of RanBP2, we expressed His-tagged SUMO2 (His6-SUMO2) in unmodified (wild type or “WT”) and RanBP2 dead E3 (“RanBP2-dE3”) human osteosarcoma (U2OS) cell lines, which we generated previously by CRISPR/Cas9." (PMID 38203469, 2023).
ovarian carcinoma (1 paper, 2025). A malignant neoplasm originating from the surface ovarian epithelium. "Since the activity of SUMOylation regulators is closely associated with global SUMOylation levels, we performed IHC for SUMO1 and SUMO2/3 on FFPE tissue sections from ovarian cancer patients at different stages." (PMID 40534859, 2025).
pancreatic ductal adenocarcinoma (1 paper, 2024). An infiltrating adenocarcinoma that arises from the epithelial cells of the pancreas. "SUMO2 conjugation to eIF5A is a stress-induced response implicated in the adaptation of yeast cells to heat-shock stress and required to promote the growth and migration of pancreatic ductal adenocarcinoma cells." (PMID 38229033, 2024).
Sepsis (1 paper, 2022). Sepsis is defined as life-threatening organ dysfunction caused by a dysregulated host response to infection. "The levels of SUMO1 and SUMO2/3 in macrophage during sepsis and the inhibitory effect of GA were unclear, which were detected by western blotting." (PMID 36743669, 2022).